CCL2 (C-C motif chemokine ligand 2)
Diseases named in the same sentence as CCL2 in open-access papers (continued):
Sharing a sentence is not in itself a finding about the gene and the disease.
asthma (continued). "Furthermore, although CCL2 may not be considered an ideal pharmacotherapeutic target for the treatment of asthma, our results indicate that HIF-1α may be used as a specific target." (PMID 22823210, 2012). "We found that TNFα treatment induced CCL2, CCL13, and IL8 mRNA expression in most fatal asthma- and non-asthma-derived ASM samples, but TNFα treatment did not induce CXCL12." (PMID 26207385, 2015). "Fatal asthma-derived ASM secreted greater TNFα-induced IL8 and lower TNFα-induced CXCL12 as compared to non-asthma-derived ASM, while TNFα-induced CCL2, and CCL13 levels between fatal asthma- and non-asthma-derived ASM were not significantly different." (PMID 26207385, 2015). "The results suggest that targeting p38 MAPK may reduce IL-6 but not other important chemokines such as MCP-1/CCL2, and that targeting STAT signaling may reduce MCP-1/CCL2 in airway smooth muscle in asthma." (PMID 25849622, 2015).
Hypertension (146 papers, 2005 to 2026). The presence of chronic increased pressure in the systemic arterial system. "The fact that higher CCL2 levels are associated with more severe organ damage in humans with hypertension underscores the clinical relevance of our findings." (PMID 38539860, 2024). "Others have previously shown that blockade or deficiency of CCL2 ameliorates mononuclear cell infiltration and target organ damage in renovascular or other forms of hypertension." (PMID 34528115, 2021). "Circulating levels of CCL2 are upregulated in hypertensive patients and correspond with the degree of hypertension-associated organ damage." (PMID 34575833, 2021). "In hypertension, increased circulating levels of angiotensin II is a potential cause for increased levels of brain CCL2." (PMID 31427987, 2019). "Additionally, the circulating levels of CCL2 are upregulated in patients with hypertension and correlate with the degree of hypertension-associated organ damage in humans." (PMID 37266014, 2023). "While elevated CCL2 in blood pressure-controlling organs has been shown, to our knowledge this is the first evidence that T cells are an important local source of CCL2 that may constitute a vital contribution to inflammation associated with hypertension." (PMID 25501574, 2014). "Thus the CCR2:CCL2 axis is an important pathway during hypertension and associated vascular disease, and may be initially driven by infiltrating T cells leading to sequalae of pro-inflammatory events." (PMID 25501574, 2014). "Hydralazine also prevented angiotensin II-induced expression of Ccr2, and its ligands Ccl2 and Ccl8, consistent with Ccr2-mediated immune cell infiltration as a key aspect of brain inflammation during hypertension." (PMID 40697973, 2025). "Elevated plasma levels of CCL2 have been found in individuals with classic risk factors for the development of coronary artery disease (CAD), such as advanced age, hypertension, hypercholesterolemia, CKD, and CVD." (PMID 39140572, 2024). "The link between high CCL2 levels and the severity of hypertension-related organ damage has been supported by correlations found in human studies." (PMID 38539860, 2024). "For example, hypertensive animals and human patients have increased levels of IL-1β, IL-6, IL-17, TNF-α, CCL-2, C-reactive protein, and adhesion molecules, while immunosuppression attenuates hypertension." (PMID 39513878, 2024). "Increased CCL2 expression due to aging induces oxidative stress, leading to vascular inflammation and subsequent arterial stiffness, which exacerbates hypertension by increasing the workload on the heart to pump blood." (PMID 39201480, 2024). "It has been observed that the rise of cytokines such as IL-6 and CCL2 in the high-salt diet-induced hypertension rat model is connected with the NLRP3 inflammatory mechanism." (PMID 36035920, 2022). "CCL2 expression was significantly elevated in the aortic tissue of animals suffering from hypertension after Ang II injection." (PMID 36110847, 2022). "Recently, we found that KLF15 negatively regulates chemokine CCL2 expression, which recruits macrophages into injured arteries in hypertension." (PMID 33869197, 2021). "CCL2 is a chemokine that contributes to the progression of hypertension by recruiting circulating monocytes to the blood vessel walls and promoting macrophage infiltration." (PMID 33906674, 2021). "There is some evidence suggesting the involvement of increased chemoattraction of immune cells by CCL2 into cardiovascular brain centers during the development of hypertension." (PMID 31427987, 2019). "Although results are sometimes conflicting, these studies implicate cytokines such as IL-1, IL-4, IL-6, IL-7, IL-13, TNF-α, and CCL2 in human hypertension." (PMID 30013513, 2018). "Previous studies have demonstrated high levels of CCL2 in patients with arterial hypertension, as well as increased levels of TNF-α on DOCA-salt models." (PMID 25878716, 2015).
Hypertension (continued). "By contrast, there was enhanced aortic CCL2 and ROS production from each T cell-infiltrate during Ang II-induced hypertension, which may represent a hypertension-specific and unique T cell phenotype that is likely to contribute to hypertension and associated vascular diseases." (PMID 25501574, 2014). "However, in the progression of Ang II-mediated hypertension, locally produced CCL2 from endothelial cells binds CCR2+ on monocytes through an “inside-out” mechanism that promotes the migration of circulating monocytes to the tunica media." (PMID 39682749, 2024). "Of note, authors used the Ang-II-infusion model of hypertension and the octapeptide may induces an increase in the CCL2 and ROS production in aorta of mice." (PMID 32848763, 2020). "Similarly, in a rodent renovascular model of hypertension, peripheral blockade of receptors for angiotensin II attenuates peripheral CCL2 production." (PMID 31427987, 2019). "CCL2 levels at radiotherapy end could be modelled using linear regression including basal CCL2, age, surgery, hypertension, and use of anticoagulants." (PMID 29682101, 2018). "Our findings suggest that a hypertension-specific function of infiltrating T cells during hypertension may be to promote further leukocyte recruitment via increased CCL2 production." (PMID 25501574, 2014). "This increase was absent in circulating or splenic T cells, and since there was increased T cell infiltration into these tissues, CCL2 production may be further amplified during hypertension." (PMID 25501574, 2014). "Since CCL2 is involved in recruiting inflammatory cells, its increased expression could lead to enhanced inflammation within the brain, contributing to the pathophysiology of hypertension." (PMID 38539860, 2024). "Furthermore, studies in models of both primary and secondary hypertension reveal upregulation of CCL2 both peripherally and centrally, with a 3-fold elevation in the levels of CCL2 within the PVN of hypertensive animals." (PMID 31427987, 2019). "Interestingly, CCL2 levels at the end of radiotherapy could be modelled through linear regression including age, abdominal surgery, hypertension, and use of anticoagulants." (PMID 29682101, 2018). "CCL2 is a vital chemokine that promotes leukocyte recruitment, and elevated production can result in an enhanced local inflammatory response, which may lead to advanced inflammation and organ dysfunction resulting in overt hypertension." (PMID 25501574, 2014). "Moreover, aortic and kidney T cells exhibit greater CCL2 and ROS production (aorta only), and represent a hypertension-specific phenotype that may promote the local inflammatory responses by recruiting leukocytes and causing oxidative stress." (PMID 25501574, 2014). "Importantly, we also identified a distinct infiltrating T cell phenotype during hypertension, where a significantly greater proportion of T cells in aorta and kidney produced CCL2, which also translated to greater amounts of CCL2 detected in conditioned media of stimulated T cells." (PMID 25501574, 2014). "Monocyte recruitment is the key factor in the development of vascular inflammation, followed by adhesion molecules (VCAM-1 and ICAM-1), inflammatory factors (TNF-α and IL-6), and chemokines (CCL2, CXCL5, CXCL8, and CXCL10) released during hypertension." (PMID 34335249, 2021). "In the PPI network, we observed that IL-6, CCL2, IL-1β, MMP-2, and MMP-9 were the hub targets of GZD for improving hypertension." (PMID 33906674, 2021). "Studies have shown that adhesion molecules ICAM-1, VCAM-1, immune cells, chemokine CCL2, and CXCR3 are key factors in human hypertension; these series of events results in the progression of hypertension." (PMID 29573749, 2018). "In a screening experiment for changes in chemokine expression in DOCA/salt-induced hypertensive mice, transcript of the chemokine CCL2 and its receptor CCR2 were increased in aortas after the onset of hypertension." (PMID 30013513, 2018).
Hypertension (continued). "Mice deficient in CCR2 exhibit decreased macrophage and monocyte infiltration into the arterial wall during Ang II-induced hypertension, suggesting that the CCR2:CCL2 axis is vital for leukocyte recruitment during hypertension." (PMID 25501574, 2014). "Furthermore, experiments blocking CCR2, the receptor for both CCL2 and CCL12, demonstrated a reduction in BP in animal models of hypertension." (PMID 38539860, 2024). "Furthermore, gut microbiota drives hypertension via the blood pressure hormone angiotensin‐II by promoting vascular inflammatory processes mediated by monocyte chemoattractant protein‐1 (MCP-1, CCL2) and IL‐17." (PMID 35451695, 2022). "They indicate that tissue expression of CCL2 and CCL5 is raised in hypertension." (PMID 34575833, 2021). "Furthermore, this process was related to a higher level of inflammatory chemokine expression (CCL2 and CCL5) in PVAT, whose crucial role in hypertension and other CVDs is well established [27,]." (PMID 33131726, 2020). "Myocardial stress, such as pressure overload or salt-induced hypertension, drives upregulation of CCR2 ligands, such as monocyte chemotactic protein-1 (MCP-1 or CCL2), MCP-3 (or CCL7), CCL12, and SDF-1alpha, which play an essential role in CCR2+ monocyte influx into the heart." (PMID 31963368, 2020). "Chemokines also take part in the pathogenesis of hypertension, including monocyte chemoattractant protein-1 (MCP-1, CCL2), Gro-α (growth-related oncogene), interferon-inducible protein (IP-10, CXCL10) interleukin-8 (IL-8; CXCL8), CXCL1/RaNTeS (CCL5)/CCR5 and fractalkine (FKN aka CX3CL1)/CX3CR1." (PMID 32848763, 2020). "Chemokines such as C-C motif chemokine ligand 2 (CCL2), and pro-inflammatory cytokines such as tumor necrosis factor alpha (TNF-α) and interleukin 1 beta (IL-1β), are upregulated both peripherally and centrally in hypertension." (PMID 31427987, 2019). "While not all human essential hypertension is angiotensin II mediated, the serum levels of CCL2 are increased in hypertensive patients." (PMID 31427987, 2019). "We found that blockade NLRP3 therapy markedly reversed hypertension, in consistent with the results reported by Krishnan, as well as significantly reduced NLRP3 pathway protein expression, decreased PICs, CCL2, CXCR3, and VCAM-1, adjusted TH, GAD67, and GABA in PVN and plasma NE." (PMID 29573749, 2018). "Sirolimus reduced renal TORC1 activation but not TORC2, NF-κB DNA binding activity, CCL2 or TNFα expression, and abnormalities in cilia ultrastructure, hypertension and cardiac disease were also not improved." (PMID 27723777, 2016). "Moreover, although chemokines such as CCL2, and ROS production have been implicated in hypertension, whether infiltrating T cells are a source of these influential mediators has not been examined in the setting of hypertension." (PMID 25501574, 2014). "Anti-CCL2 (Carlumab), for example, has shown potential in reducing inflammation in several conditions, although it has not been extensively tested in models of hypertension." (PMID 40859641, 2025). "However, the extent to which CCL2 and the chemoattraction of immune cells contribute to increased SNA and BP in the development of hypertension is still unknown and requires further investigation." (PMID 31427987, 2019). "Ang II-induced hypertension does not affect the overall T cell cytokine profile, but enhanced T cell-derived ROS production and/or leukocyte recruitment due to elevated CCL2, and this effect may be further amplified with increased infiltration of T cells." (PMID 25501574, 2014).
metabolic syndrome (139 papers, 2008 to 2026). A cluster of metabolic risk factors for CARDIOVASCULAR DISEASES and TYPE 2 DIABETES MELLITUS. "MCP-1/CCL2 upregulation associates with metabolic syndrome–induced male subfertility in both mice and men." (PMID 33148888, 2020). "MUO patients exhibited higher HIF1A expression (p = 0.03) and strong correlations between CCL2 and dyslipidemia (total cholesterol, triglycerides)/dysglycemia (fasting glucose) (r = 0.45, p = 0.03; r = 0.52, p = 0.01; r = 0.63, p = 0.001, respectively)." (PMID 40943138, 2025). "Testicular CCL2 has been reported to be correlated to hypogonadism and is upregulated in testes of mice with metabolic syndrome." (PMID 37221631, 2023). "Our findings show that prolonged exposure to CN attenuated increased levels of nitrotyrosine and CCL2, biomarkers of inflammation in the arteries of metabolic syndrome rats." (PMID 36670944, 2022). "The abundance of the mRNA of Ccl2 has been shown to positively correlate with that of CD11c in visceral adipose of obese humans with metabolic syndrome compared with lean humans." (PMID 34432833, 2021). "Horses with metabolic syndrome showed marked adipocyte hypertrophy and increased expression of adipokines (leptin) and inflammatory cytokines (TNFα,IL1β and CCL2) in both adipose tissue depots compared to healthy horses." (PMID 30866087, 2019). "Notably, the neutralization of CX3CL1 or CCL2 activity on HUAEC led to a decrease in platelet-leukocyte endothelial adhesion in the metabolic syndrome group only after TNFα stimulation of HUAEC." (PMID 31109070, 2019). "Additionally, CX3CL1/CX3CR1 or CCL2/CCR2 axes are potential candidates for therapeutic intervention in cardiovascular disorders in metabolic syndrome patients, as their blockade impairs the augmented arterial platelet-Mon1 monocyte aggregate adhesiveness, which is a key event in atherogenesis." (PMID 31109070, 2019). "The chemokine member CCL2 was highly expressed in adipose tissue and contributed to the cells becoming insulin resistant while CXCL2 (or MIP-2), encoding macrophage inflammatory protein 2-alpha (MIP2-alpha), was the main marker of inflammatory reaction in metabolic syndrome." (PMID 27551318, 2016). "We characterized immune cell behavior in metabolic syndrome, its consequences, and the potential involvement of the CX3CL1/CX3CR1 and CCL2/CCR2 chemokine axes." (PMID 31109070, 2019). "Remarkably, the inhibition of MCP1/CCL2 induces an improvement of steatohepatitis and metabolic syndrome." (PMID 25668433, 2015). "When most of the Treg cells were ablated, pro-inflammatory transcripts (e.g., RANTES and CCL2) were strongly induced in the fat tissue, suggesting that the anti-inflammatory properties of Treg cells may have therapeutic potential to inhibit elements of the metabolic syndrome." (PMID 20936118, 2010). "The neutralization of either CX3CL1 or CCL2 activity on HUAEC again markedly reduced TNFα-induced leukocyte adhesion in the metabolic syndrome group, but not in the control group." (PMID 31109070, 2019). "Altered levels of distinct chemokines, like CCL5/RANTES, CXCL12/SDF-1a, CCL7/MCP-3, CCL2/MCP-1, CXCL1/GROa, and the eotaxin family, contribute to the development and/or exacerbation of inflammation, which is a common feature of numerous skin diseases as well as metabolic syndrome." (PMID 42042898, 2026). "A study investigating serum levels of CCL-2 in patients with DM and metabolic syndrome (MetS) found that serum CCL-2 levels were significantly increased in the MetS group and the DM group." (PMID 35603204, 2022).
ovarian carcinoma (135 papers, 1999 to 2025). A malignant neoplasm originating from the surface ovarian epithelium. "Cancer-associated mesothelial cells enhance epithelial ovarian cancer cell invasion by generating CCL2 through the P38 pathway." (PMID 37445830, 2023). "We demonstrated that high levels of CCL2 in ovarian cancer are associated with paclitaxel resistance via autocrine signaling and macrophage recruitment." (PMID 36766725, 2023). "CCL2 secreted from cancer-associated mesothelial cells promotes peritoneal metastasis of ovarian cancer cells through the P38-MAPK pathway." (PMID 32337264, 2020). "In this report, we describe the characterisation of CCL2 expression in a larger panel of ovarian cancer cell lines and primary tumours and mutation analysis of the CCL2 gene in primary ovarian adenocarcinomas." (PMID 15900302, 2005). "However, the underlying mechanisms and possible roles of CCL2 in regulating ovarian cancer remain unclear." (PMID 37445830, 2023). "Paclitaxel-resistant ovarian cancer cells were shown to overexpress CCL2, which not only promoted chemoresistance via PI3K/Akt and NF-κB signaling pathways but also attracted TAMs." (PMID 40330466, 2025). "CCL2 released by omental adipocytes facilitates the migration and omental metastasis of ovarian cancer through the activation of PI3K/AKT/mTOR followed by an increase in HIF-1α and vascular endothelial growth factor A (VEGF-A)." (PMID 40076892, 2025). "Serum levels of CCL2 are also high in patients with ovarian cancer, nasopharyngeal carcinoma, and pancreatic cancer compared to healthy subjects." (PMID 40076892, 2025). "These exosomes also secrete CXCL5 and CCL2, which interact with receptors on tumor cells to accelerate the peritoneal metastasis of ovarian cancer." (PMID 40109727, 2025). "Ovarian cancer chemokine landscape profiling revealed chemokines such as CCL2, CCL4, CCL5, CXCL10, and CXCL12 as potential candidates in ovarian cancer." (PMID 41424784, 2025). "Combining anti − CCL2 antibody therapy with chemotherapy or immunotherapy in a mouse ovarian cancer model has improved the antitumor effects." (PMID 39003350, 2024). "As per chemokines, CCL2 stimulates the proliferation of ovarian cancer cells via the MAPK/ERK pathway." (PMID 39595551, 2024). "Our previous study reported that the recombinant CCL2 protein promoted ovarian cancer cell activity." (PMID 37445830, 2023). "The serum CCL2 level in patients with primary ovarian cancer is higher than that in patients with benign ovarian cysts and healthy people." (PMID 37445830, 2023). "Our previous study demonstrated that exogenous CCL2 promotes ovarian cancer cell proliferation by stimulating ERK signaling and regulating the JUN, RELB, and NF-κB2 expressions." (PMID 37445830, 2023). "The present study evaluated the vital role of CCL2 in ovarian cancer and explored the mechanism of CCL2 in the development of ovarian cancer." (PMID 37445830, 2023). "In this work, we evaluated the vital role of CCL2 in ovarian cancer and explored the mechanism of CCL2 in the development of ovarian cancer." (PMID 37445830, 2023). "The MYBL2/CCL2 axis contributing to TAMs recruitment and M2-like polarization is crucial to immune evasion and anti-PD-1 resistance in ovarian cancer, which is a potential target to enhance the efficacy of immunotherapy." (PMID 37865750, 2023). "The function of CCL2 knockout in inhibiting ovarian cancer cell proliferation, migration, and invasion was investigated further to confirm the biological roles of CCL2 in ovarian cancer." (PMID 37445830, 2023). "The present study demonstrated that mitogen-activated protein three kinase 19 (MAP3K19) was the key CCL2 target for regulating ovarian cancer progression through transcriptome sequencing." (PMID 37445830, 2023). "Transcriptome sequencing demonstrated that MAP3K19 was the key target for CCL2 in regulating ovarian cancer progression." (PMID 37445830, 2023).